CDC20 (cell division cycle 20)
Diseases named in the same sentence as CDC20 in open-access papers (continued):
Sharing a sentence is not in itself a finding about the gene and the disease.
pancreatic cancer (continued). "In the current study, we explore whether curcumin exhibits its anti-cancer function through inhibition of oncoprotein cell division cycle 20 (Cdc20) in pancreatic cancer cells." (PMID 28165402, 2017). "Moreover, we observed that curcumin significantly inhibited the expression of Cdc20 in pancreatic cancer cells." (PMID 28165402, 2017). "Furthermore, our results demonstrated that overexpression of Cdc20 enhanced cell proliferation and invasion, and abrogated the cytotoxic effects induced by curcumin in pancreatic cancer cells." (PMID 28165402, 2017). "CDC20 overexpression has been detected in pancreatic cancer tissue and cell lines." (PMID 22475564, 2012). "CDC20 may also be involved in the role of KIF2C in pancreatic cancer." (PMID 36900292, 2023). "Therefore, our findings indicated that inhibition of Cdc20 by curcumin could be useful for the treatment of pancreatic cancer patients." (PMID 28165402, 2017). "Eight genes (BUB1, BUB1B, CCNA2, CCNB2, CDC6, CDC20, CDK1, and TTK) among 21 common network genes were correlated with worse survival of pancreatic cancer, highlighted with P-value significantly <0.05." (PMID 32117719, 2020). "Mechanistically, suppression of SPRY4-IT1 inhibited the expression of Cdc20, whereas overexpression of SPRY4-IT1 increased Cdc20 level in pancreatic cancer cells." (PMID 29489909, 2018). "We used qRT-PCR to determine CDC20 transcript levels in five normal pancreatic tissue samples, five pancreatitis tissue samples, six PDAC tissue samples, and seven pancreatic cancer cell lines (Panc-48, Panc-1, AsPC-1, CFPac-1, Panc-3, Panc-28, and Capan-2)." (PMID 22475564, 2012). "Our findings suggested that CDC20 overexpression, particularly in myocardial cells, could effectively inhibit DOX-induced cardiomyocyte apoptosis, while also inhibiting pancreatic carcinoma and melanoma growth." (PMID 40045239, 2025). "Moreover, UBE2S could form an important ubiquitin ligase APC/C with ANAPC2/4, whereas CDC20 could regulate APC/C, activating other significant factors in EMT progression, such as E-cadherin by ubiquitin, to affect the invasion and metastasis of pancreatic cancer." (PMID 37682144, 2023).
bladder cancer (30 papers, 2011 to 2025). "In conclusion, we have identified potential prognostic biomarkers by WGCNA, using data from TCGA and GEO databases to confirm a significant association between CDC20 expression and overall survival of bladder cancer patients." (PMID 41374402, 2025). "Consistent with our research, increased expression of CDC20 in bladder cancer patients is associated with poor prognosis." (PMID 32047816, 2020). "Given the differences in assay platform, time, location, and dosage between the four experiments, it is encouraging to find shared genes that are relevant biologically; EGFR, CDK6, and CDC20 play key functions in cell cycle progression and have been implicated in bladder cancer." (PMID 37415126, 2023). "Therefore, the results of the multifactorial analysis show that cell cycle protein B1 (CCNB1) and cell division cycle 20 (CDC20) are risk factors for the prognosis of carcinoma of urinary bladder patients." (PMID 35280820, 2022). "Previous studies have shown abnormal expression of CDC20 in bladder cancer tissue that may serve as a potential diagnostic biomarker for NMIBC." (PMID 34885040, 2021). "The findings revealed a significant inhibition in the proliferation of both bladder cancer cell lines upon reduction in CDC20 expression." (PMID 41374402, 2025). "In summary, through WGCNA and validation using datasets from TCGA and GEO databases, we have identified potential prognostic biomarkers, demonstrating a significant correlation between CDC20 expression levels and overall survival in bladder cancer patients." (PMID 41374402, 2025). "The results illustrated a reduction in the number of clones formed by bladder cancer cells following CDC20 knockdown, indicating a suppressive effect on cell proliferation." (PMID 41374402, 2025). "Further experimental studies are needed to fully elucidate the molecular mechanisms of CDC20 in bladder cancer progression and treatment." (PMID 41374402, 2025). "The protein–protein interaction network analysis of CDC20 interactions using the “ComPPI” website provided insights into the molecular interactions of CDC20 with other proteins involved in bladder cancer." (PMID 41374402, 2025). "The bioinformatics approach utilized in this study provides a new perspective to explore the role of CDC20 in bladder cancer and offers valuable insights into the development of anticancer drugs as well as feasible gene therapy strategies." (PMID 41374402, 2025). "In summary, these results support the idea that Cdc20 depletion endows bladder cancer cells with sensitivity to ER stress‐induced cellular apoptosis mainly via the reduced degradation of TPD52." (PMID 39401430, 2024). "In a previous work we have performed a similar approach for urinary bladder cancer, where we have reported that a single gene (CDC20) manifested a common profile among different subtypes of urothelial bladder cancer." (PMID 34204289, 2021). "Studies have demonstrated that CDC20 overexpression decreases overall survival and recurrence-free survival time in bladder cancer patients." (PMID 34885040, 2021). "According to the results, increasing the expression of CDC20 increases the incidence of death from bladder cancer (or progression of the disease) by 2.68 times." (PMID 34589136, 2021). "Surprisingly, the expression levels of CDC20 and ASPM are associated with the prognosis of patients with bladder cancer." (PMID 32047816, 2020). "Early research has demonstrated that CDC20 is highly expressed in multiple tumors, and is related to the poor prognosis of patients with gastric cancer, liver cancer, bladder cancer, colon cancer, and NSCLC." (PMID 33186389, 2020). "In vitro, we interfered with the expression of ASPM and CDC20 and then used the cell counting kit-8 experiment and clone formation experiment to detect the effect on the proliferation of bladder cancer T24 cell line." (PMID 32047816, 2020).
bladder cancer (continued). "The results showed that the expression levels of ACTA2, CCNB1, CDC20 and VEGFA were associated with the prognosis of patients with bladder cancer." (PMID 30533316, 2018). "Furthermore, gene set enrichment analysis revealed CDC20’s involvement in facilitating the progression of bladder cancer." (PMID 41374402, 2025). "Importantly, we demonstrated that CDC20 is upregulated in bladder cancer tissues and cell lines, and this elevated expression predicts poorer survival outcomes." (PMID 41374402, 2025). "Moreover, there were pieces of evidence indicating that CDC20 accounted for the promotion of radio-resistance of bladder cancer by inducing the degradation of FoxO1." (PMID 35622386, 2022). "However, the copy number variation (CNV) of CDC20 shows amplification in various cancers including ovarian cancer, bladder cancer, cervical cancer, etc." (PMID 33851100, 2021). "In summary, using a series of bioinformatics and retrospective analyses, the present study identified a subset of seven genes (CDC20, CDKN2A, CTSV, FOXM1, KRT23, MAGEA6, and S100A9), which were significantly associated with progression and prognosis of bladder cancer." (PMID 34885040, 2021). "In addition, the biological role of the ASPM and CDC20 molecules in the development of bladder cancer was confirmed by in vitro experiments." (PMID 32047816, 2020). "In addition, we interfered with the expression of ASPM and CDC20 in vitro and then used the cell counting kit-8 experiment and clone formation experiment to detect the effect on the proliferation of bladder cancer T24 cell line." (PMID 32047816, 2020). "Among them, TOP2A, CDC20, CDCA5 and UBE2C all act as oncogenes in bladder cancer and promote tumor progression." (PMID 36932399, 2023). "The expression profile of CDC20, CDKN2A, CTSV, FOXM1, KRT23, MAGEA6, and S100A9 were significantly higher in bladder cancer specimens compared with normal bladder tissue in patients." (PMID 34885040, 2021). "The PPI network analysis of three databases identified the following subsets of DEGs, including CDC20, CDKN2A, CTSV, FOXM1, KRT23, MAGEA6, and S100A9, which were significantly upregulated in bladder cancer." (PMID 34885040, 2021). "We found mRNA expression of AURKA, CDCA8, CDC20 were decreased upon knockdown of PUF60 by its specific siRNA, indicating that they are the potential downstream targets of PUF60 in bladder cancer (indicated by the arrows)." (PMID 33117697, 2020). "Survival analysis revealed that the expression levels of ACTA2, CCNB1, CDC20 and VEGFA were related to the prognosis of patients with bladder cancer." (PMID 30533316, 2018). "Hub genes (CCNB2, CDC20) are highly expressed in OSCC and bladder cancer samples." (PMID 36820589, 2023). "We believe that CDC20 and ASPM may affect the development of bladder cancer by affecting TOX molecules." (PMID 32047816, 2020). "Notably, among these genes, CDC20 exhibited a negative correlation with prognosis, suggesting its potential as a prognostic indicator in bladder cancer." (PMID 41374402, 2025). "A total of seven genes, including CDKN2A, CDC20, CTSV, FOXM1, MAGEA6, KRT23, and S100A9 were confirmed with strong prognostic values in bladder cancer and validated by qRT-PCR conducted in various human bladder cancer cells representing stage-specific disease progression." (PMID 34885040, 2021). "In conclusion, we believe that these five target genes (GSK3B, CDC20, TPX2, AURKA and CCNE1) may promote the occurrence of bladder cancer and lead to poor prognosis.We explored the potential therapeutic targets of aspirin for bladder cancer by comprehensive bioinformatics analysis." (PMID 36316768, 2022). "To further evaluate the clinical correlation between Cdc20 and TPD52, we performed immunohistochemical (IHC) staining in bladder cancer patient samples and found a negative correlation (Rho = ‐0.1928, P = 0.0206) between the two proteins." (PMID 39401430, 2024).
colorectal cancer (28 papers, 2013 to 2025). A primary or metastatic malignant neoplasm that affects the colon or rectum. "CDC20 has been implicated in colorectal cancer, and its expression levels are positively correlated with advanced clinical stages, metastasis, and decreased survival rates, highlighting its potential as a key biomarker for diagnosing and predicting the prognosis of the disease." (PMID 39795587, 2024). "Overexpression of CDC20 was proved to be associated with a prognostic marker for colorectal cancer." (PMID 35053185, 2021). "Elevated expression of CDC20 was observed in cell lines of colorectal cancer, with levels positively correlated with late clinical-stage, metastasis, and lower survival rates." (PMID 37383715, 2023). "We noticed that CDC20 expression in colorectal cancer (CRC) is especially higher, and increased CDC20 expression is closely related to the clinicopathological progression of CRC." (PMID 32932732, 2020). "In this study, we determined that targeting cell division cycle 20 (CDC20) radiosensitized colorectal cancer (CRC) cells through mitochondrial-dependent apoptotic signaling." (PMID 32932732, 2020). "We further analyzed the link between CDC20 expression and the clinical characteristics of colorectal cancer in 244 paraffin-embedded, archival primary colorectal cancer tissues by IHC." (PMID 23758705, 2013). "CDC20 expression was evaluated in colorectal cancer cell lines and tissues to investigate the role of CDC20 in tumorigenesis." (PMID 23758705, 2013). "Furthermore, another study revealed that CDC20 expression increased more than fivefold in 77% of colorectal cancer tissues." (PMID 39795587, 2024). "However, a separate independent study reported that CDC20 expression was lower in colorectal cancer tissues compared to normal tissues." (PMID 39795587, 2024). "Moreover, in colorectal cancer models CDC20 regulated MCL-1 expression levels and its downregulation increased radiosensitivity and induced apoptosis, while BAK, BAX, PUMA, BCL-2, and BCL-xL levels were not affected by the silencing." (PMID 35490245, 2022). "Additionally, high expression of CDC20 was significantly associated with overall survival in advanced clinical stage (stage III and IV) patients with colorectal cancer." (PMID 33922264, 2021). "CDC20 is overexpressed in a variety of human tumors including colorectal cancer (CRC)." (PMID 32932732, 2020). "Patients with colorectal cancer overexpressing CDC20 had a shorter overall survival." (PMID 31106147, 2019). "Moreover, multivariate analysis indicated that N classification, M classification, pathologic differentiation and CDC20 expression were independent prognostic factors for colorectal cancer." (PMID 23758705, 2013). "CDC20 overexpression has been detected in many types of human cancers; however, its clinical role in colorectal cancer remains unknown." (PMID 23758705, 2013). "Interestingly, HSH2D expression did not correlate with other genes associated with colorectal cancer metastasis and tumorigenesis, namely CDC20 and BIRC5." (PMID 39405604, 2024). "CDC20 may serve as a potential prognostic biomarker of human colorectal cancer." (PMID 23758705, 2013). "Furthermore, CDC20 may serve as a potential prognostic biomarker of human colorectal cancer." (PMID 35800227, 2022). "Interestingly, CDC20 expression in colorectal cancer showed a negative correlation with patient survival time (P < 0.001)." (PMID 23758705, 2013). "Moreover, the mRNA expression levels of CDC20 and MAD2 also exhibited a negative correlation with the aneuploidy score in colorectal cancer." (PMID 39018254, 2024).
gastric cancer (25 papers, 2012 to 2025). A primary or metastatic malignant neoplasm involving the stomach. "In gastric cancers, CDC20 upregulation is positively associated with tumor size, histological grade, and TNM stage, while its elevated expression is also correlated with worse survival outcomes." (PMID 39795587, 2024). "High CDC20 levels appear to be associated with several other cancers, including serous epithelial ovarian cancer, gastric cancer, oral cancer, and adult T-cell leukemia; high levels are also found in oral squamous cell carcinoma-derived cell lines and the HT29 human adenocarcinoma cell line." (PMID 22475564, 2012). "Importantly, CDC20 upregulation is associated with several types of cancer including breast and colon cancer and has been involved in aggressive tumor progression and poor prognosis in gastric cancer and primary non-small cell lung cancer." (PMID 38523261, 2024). "Conversely, a study of 131 FFPE gastric cancer tissues identified a positive correlation between CDC20 overexpression and advanced cancer stage." (PMID 39795587, 2024). "CDC20 overexpression is reported to promote the development of colorectal, pancreatic, non-small cell lung, and gastric cancers." (PMID 35223804, 2022). "CDC20 upregulation has been reported in astrocytoma and gastric cancer, and in HCC the overexpression of this gene is associated with disease onset and progression." (PMID 36217480, 2022). "Previous studies have reported aberrantly high expression levels of CDC20 in oral squamous cell carcinoma, gastric cancer, and lung adenocarcinoma." (PMID 33718368, 2021). "For example, 51.9% of gastric cancer tissues showed high CDC20 expression, but only 18.3% showed high expression in the adjacent noncancerous tissues." (PMID 27991546, 2016). "The detection of cdc20 mRNA by qPCR in gastric cancer tissues showed that the mean expression value of cdc20 mRNA in cancer tissues was significantly higher than in normal tissues." (PMID 27991546, 2016). "CDC20 is overexpressed in various gastric cancer tumor tissues." (PMID 39795587, 2024). "CDC20 has been found to be upregulated in lung, pancreatic, and gastric cancers, as well as in CC." (PMID 23405241, 2013). "However, CBX4 may contribute to OSCC progression by regulating genes involved in cell cycle and stemness, such as CDC20, as observed in gastric cancer studies." (PMID 40740235, 2025). "Indeed, Cdc20 upregulation has been demonstrated in several types of cancers, including breast and colon cancer, and it contributes to aggressive tumor progression and poor prognosis in gastric cancer and primary non-small cell lung cancer." (PMID 39412391, 2024). "Moreover, the co-delivery of drugs and CDC20 siRNA strongly inhibited gastric cancer cell growth." (PMID 35223804, 2022). "Moreover, increased abundance of securin, CDC20 and UBE2C were shown to be predictors of poor survival in patients with various cancers, including breast, colorectal, and gastric cancers." (PMID 35456956, 2022).
liver cancer (19 papers, 2017 to 2026). An epithelial or non-epithelial malignant neoplasm that arises from the liver. "Principally, CDCA5 (AUC = 0.978) and CDC20 (AUC = 0.957) showed excellent diagnostic specificity and sensitivity and could be considered key oncogenic genes in liver cancer." (PMID 36685860, 2022). "The combination of CCNB1 and CDC20 high expression could predict the poor prognosis of liver cancer, similar to what we got in ACC." (PMID 35983531, 2022). "There was also evidence that CDC20 molecules may activate the cell cycle of liver cancer cells, leading to a poor prognosis for liver cancer patients." (PMID 35800227, 2022). "MCM6, CDC20, and PCNA are also associated with prognosis in liver cancer." (PMID 32082966, 2019). "Meanwhile, immunohistochemical results of AURKA, CCNB1, CDC20 and TOP2A were found through the HPA database, which also confirmed that there were significant differences between liver cancer tissues and normal adjacent tissues." (PMID 39537209, 2024). "GTSE1, together with CDC20, PCNA, and MCM, presented unfavorable prognosis of liver cancer in our study." (PMID 32082966, 2019). "Notably, CAMK2B showed medium expression in both normal and liver cancer tissues, while CDC20 and PPP1CA were undetected in normal tissue but exhibited medium expression in liver cancer." (PMID 41511815, 2026). "The results demonstrated the up-regulation of BOP1, CDC20, and UBE2S in liver cancer cells." (PMID 38577593, 2024). "Among the DEGs, CDC20, PCNA, and MCM6 might synergistically affect regulations in cell cycle with GTSE1 and might be potential prognostic predictors in liver cancer." (PMID 32082966, 2019). "The top modular genes, TOP2A, CDC20, PRC1, CCNB2, and NUSAP1, were highly associated with HCC onset and development; high expression of TOP2A, CDC20, or CCNB2 was correlated with poor survival time in TCGA liver cancer patients, implying their potential as biopsy-based prognostic markers." (PMID 31001331, 2019). "Genes like GTSE1, CDC20, PCNA, and MCM6 may be promising prognostic molecular biomarkers in liver cancer." (PMID 32082966, 2019).